ORAI1 (ORAI calcium release-activated calcium modulator 1)
Diseases named in the same sentence as ORAI1 in open-access papers (continued):
Sharing a sentence is not in itself a finding about the gene and the disease.
cardiac hypertrophy (continued). "Several data demonstrated that Orai1 participates actively in SOCE and might be implicated in the development of diseases such as arrhythmias, cardiac fibrosis or hypertrophy." (PMID 29618985, 2018). "Also, the knockdown of Orai1 attenuated Ang II-induced pathological cardiac hypertrophy." (PMID 34079454, 2021). "Therefore, this study examined changes in vagal discharge and investigated whether pyridostigmine can inhibit CaN/NFAT3/GATA4 and suppress Orai1/STIM1 complex formation as well as improve cardiac function in pressure overload‐induced cardiac hypertrophy." (PMID 28296184, 2017). "TRPCs and Orai1 are upregulated, and STIM1 is activated, during the progression of cardiac hypertrophy." (PMID 34564947, 2021). "Together, these data suggest that Orai1, as the main mediator of SOCE, promoted Ang II-induced cardiac hypertrophy in the C57 animal model (in vivo) and cultured cell (in vitro)." (PMID 34079454, 2021). "For example, induction of cardiac hypertrophy by pressure overload results in upregulation of STIM1 and Orai1 expression in mouse cardiac tissue, and cardiomyocyte-specific suppression of STIM1 and Orai1 attenuates the hypertrophic response." (PMID 32086252, 2020). "We demonstrated that gastrodin attenuated the cardiac hypertrophy and suppressed the SOCE via its action on Orai1 and STIM1 expression." (PMID 28487655, 2017). "Taken together, this study demonstrated that gastrodin attenuated the cardiac hypertrophy and suppressed the SOCE via its action on Orai1 and STIM1 expression." (PMID 28487655, 2017). "In our study, pyridostigmine inhibited the expression of CaN, NFAT3, p‐GATA4 and STIM1, prevented Orai1/STIM1 complex formation and attenuated cardiac hypertrophy." (PMID 28296184, 2017). "Together, these results showed that gastrodin inhibited cardiac hypertrophy and it also reduced the SOCE via its action on the expression of STIM1 and Orai1." (PMID 28487655, 2017). "(c) Suppression of SOCE by an Orai1 inhibitor RO2959, Orai1-siRNAs, or STIM1-siRNAs all attenuated the phenylephrine-induced hypertrophy, demonstrating a critical role of SOCE, STIM1 and Orai1 in promoting cardiac hypertrophy." (PMID 28487655, 2017). "Understanding the mechanism of STIM1, Orai1 and TRPC1 may prevent cardiac hypertrophy or heart failure." (PMID 35303866, 2022). "Since STIM1, Orai1, and TRPCs are central mediators of SOCE, directly interfering with their expressions through the corresponding knockdowns and knockouts can help to elucidate the specific role of SOCE during the progression of cardiac hypertrophy." (PMID 34564947, 2021). "The cardiac hypertrophy level was similar, however, Orai1+/– mice were no longer able to compensate the chronic pressure overload, resulting in the development of a more severe systolic dysfunction." (PMID 33117812, 2020). "Similarly, pharmacological induction of cardiac hypertrophy by phenylephrine and endothelin-1 is attenuated by suppression of STIM1 or Orai1 in rodent cardiomyocytes." (PMID 32086252, 2020). "In the present study, pyridostigmine may have suppressed the formation of Orai1/STIM1 complex, resulting in inhibition of the activation of the CaN/NFAT3/GATA4 signalling pathway and attenuation of cardiac hypertrophy." (PMID 28296184, 2017). "In our conditions, inhibiting Orai1 did not prevent the development of cardiac hypertrophy." (PMID 31906693, 2020). "Pyridostigmine attenuated cardiac hypertrophy and improved cardiac function, which was related to improved cholinergic transmission efficiency (decreased acetylcholinesterase and increased acetylcholine), inhibition of the CaN/NFAT3/GATA4 pathway and suppression of the interaction of Orai1/STIM1." (PMID 28296184, 2017).
acute pancreatitis (13 papers, 2015 to 2025). An acute inflammatory process that leads to necrosis of the pancreatic parenchyma. "Auxora, the i.v. formulation of the Orai1 selective blocker zegocractin (CM4620) has been tested in several clinical trials (Phase I/II) including studies targeting patients with acute pancreatitis or COVID-19 pneumonia." (PMID 41212057, 2025). "It is worth mentioning that several ORAI1 inhibitors have been developed and tested in diverse disorders including asthma, COVID-19 pneumonia, refractory lymphomas, and acute pancreatitis." (PMID 39594579, 2024). "Roles for calcium entry and plasma membrane calcium exporters in acute pancreatitis have been shown, including calcium entry through the Orai1 and Piezo1/TRPV4 transporters." (PMID 39010833, 2024). "In Waldron’s study, the Orai1 inhibitor CM4620 was found to alleviate acute pancreatitis in rats, decreasing neutrophil oxidation bursts and inflammatory gene expression during pancreatitis." (PMID 35627260, 2022). "Cytosolic calcium overload, mediated via ORAI1, contributes to the pathogenesis of acute pancreatitis." (PMID 25917787, 2015). "We investigated the roles of ORAI1 in pancreatic acinar cell injury and the development of acute pancreatitis in mice." (PMID 25917787, 2015). "Agents that trigger acute pancreatitis, such as alcohol and fatty acid ethyl esters, induce a sustained elevation of cytosolic Ca2+ due to Orai1-based CRAC channel opening, which leads to the activation of trypsin within endocytic vacuoles and mitochondrial Ca2+ overload, disrupting ATP production." (PMID 40459545, 2025). "Indeed, the Orai1 blocker Auxora has already been tested in phase II clinical trials for the treatment of acute pancreatitis, severe acute kidney injury (NCT06374797), and severe COVID-19 pneumonia." (PMID 41212057, 2025). "Likewise, mitigation of SNI-induced pain hypersensitivity was replicated by CM4620, a small-molecule Orai1 antagonist that is currently in clinical trials for mitigating inflammation in human patients with acute pancreatitis and COVID-19 pneumonia." (PMID 36706180, 2023). "As SOCE is essential to develop sustained and pathological elevation of [Ca2+]i and ORAI1 inhibitors were reported to mitigate the severity of acute pancreatitis, our data raise the possibility that TRPM4 plays a preventive role in the pathophysiology of Ca2+ signaling." (PMID 34329682, 2021). "Furthermore, CalciMedica developed a selective Orai1 inhibitor, termed AuxoraTM, that showed a safety profile and tolerability in a Phase 2b clinical trial for the treatment of acute pancreatitis (AP) with accompanying systemic inflammatory response syndrome (SIRS)." (PMID 40558483, 2025). "In a mouse model of acute pancreatitis induced by Ca2+ overload they observed puncta-like colocalization of STIM1 and Orai1 and an increase in SOCE." (PMID 35821821, 2022). "ORAI1 inhibition could inhibit SOCE and necrosis in human pancreatic acinar cells and ameliorate acute pancreatitis." (PMID 25917787, 2015).
asthma (13 papers, 2012 to 2025). "Strategies that target Orai1 or the BPIFA1 deficiency in asthma may lead to novel therapies to treat this disease." (PMID 28165446, 2017). "Taken together, these data strongly indicated that Orai1 was more active in asthma and CF than in normal lungs." (PMID 40589325, 2025). "Ca2+ influx/Orai1 activity is defective in airway smooth muscle from asthma patients and in murine asthma models." (PMID 40589325, 2025). "Some compounds have undergone clinical trials due to the involvement of Orai1-Ca2+ signaling in psoriasis, pancreatitis, asthma, pneumonia, and acute kidney injury." (PMID 41212057, 2025). "Conversely, inhibition of Orai1 has been proposed as a therapeutic for asthma, CF, acute respiratory distress syndrome (ARDS) and other lung diseases." (PMID 40589325, 2025). "ORAI1 is also commonly reported as a target for diseases implicating inflammatory processes, including arthritis, asthma, cancer, conjunctivitis, COVID-19, pancreatitis, pneumonia, psoriasis, or rheumatism." (PMID 38516893, 2024). "Studies have shown that the expression of STIM1 and ORAI1 proteins is positively modulated in the smooth muscle cells of tracheal and bronchial tissues in ovalbumin-challenged asthma models." (PMID 39664985, 2024). "Reducing the expression of these proteins inhibits smooth muscle cell chemotaxis and proliferation, underscoring the role of STIM1 and ORAI1 in smooth muscle remodeling in asthma." (PMID 39664985, 2024). "The reduced gene expression of these proteins significantly inhibited chemotactic migration and smooth muscle cell proliferation, highlighting the role of STIM1 and Orai1 as targets for smooth muscle remodeling during asthma." (PMID 37841931, 2023). "Studies have shown that the expression of STIM1 and Orai1 proteins was positively modulated in smooth muscle cells of tracheal and bronchial tissue isolated from ovalbumin-challenged mice with asthma." (PMID 37841931, 2023). "Moreover, we propose that STIM1-Orai1 co-localization (Orai1 activation) can be used as a biomarker of inflammation in asthma, CF and other lung diseases." (PMID 40589325, 2025). "Ca2+release–activated Ca2+ channel protein ORAI1 promotes Th2 cell functions in asthma." (PMID 37377967, 2023). "Another Orai1 inhibitor (RP3128) has reached clinical trials (Phase I/IIa) for asthma." (PMID 34944425, 2021). "Our findings suggest that STIM1 and Orai1 may be important molecules responsible for airway remodeling in asthma." (PMID 22984609, 2012). "Because the present and previous results have demonstrated that SOCE tightly regulates the contraction, proliferation, and migration of ASM cells, STIM1 and Orai1 may be involved in mechanisms of the pathophysiology of airway diseases such as asthma and COPD." (PMID 22984609, 2012). "In lungs from asthma and CF patients, STIM1-Orai1 co-localization was significantly increased, which is indicative of more Orai1 activation." (PMID 40589325, 2025). "In murine models of asthma, blocking CRAC channels effectively prevents Th2 cell-mediated responses, while mast cells from STIM1 or ORAI1 knockout mice exhibit impaired degranulation and reduced activation of transcription factors NF-AT and NF-κB." (PMID 39664985, 2024). "Since 2006 and the identification of Orai1 as the archetype of SOCE, Orai1 has been a potential target in several pathological processes, including psoriasis, pancreatitis, asthma, and COVID-19 pneumonia." (PMID 34944425, 2021). "Since the identification of the Orai1 Ca2+ channel as the archetype of SOCE, Orai1 is now considered a plausible target in several pathological processes, including left heart failure, asthma, pancreatitis, muscular myopathy, inflammation, thrombocytopenia, and PAH." (PMID 41212057, 2025). "Indeed, SPLUNC1 acts as a gene modifier in both CF and asthma and we speculate that reduced SPLUNC1 levels may aberrantly increase Orai1 levels and SOCE in both diseases, leading to increased inflammation." (PMID 35581745, 2022).
atopic dermatitis (13 papers, 2012 to 2023). "Based on the genetic association study, For example, Orai1 polymorphisms have been shown to associate with the susceptibility for recurrence of calcium nephrolithiasis, Kawasaki disease and atopic dermatitis." (PMID 33348924, 2020). "For example, rs6486795 of the ORAI1 gene was associated with various diseases, including atopic dermatitis in Japanese and Taiwanese populations and nephrolithiasis in a Taiwanese population." (PMID 33182378, 2020). "SNPs of the ORAI1 gene region and/ or their combinations have been associated with other inflammatory diseases as well, such as atopic dermatitis, ankylosing spondylitis or rheumatoid arthritis and calcium nephrolithiasis." (PMID 26789410, 2016). "Previous studies reported significant associations between genetic polymorphisms of ORAI1 and inflammatory diseases such as ankylosing spondylitis, calcium nephrolithiasis, and atopic dermatitis." (PMID 24808640, 2014). "Previous genetic polymorphism studies in Japanese and Taiwanese populations indicated that genetic variants of the ORAI1 gene, which encodes a membrane calcium channel subunit, contribute to the susceptibility to atopic dermatitis." (PMID 24069052, 2013). "Haplotype C-G-C-A (rs3741595, rs3741596, rs3825175, and rs712853) of ORAI1 was significantly associated with atopic dermatitis." (PMID 22253717, 2012). "Our results suggest that an electrostatic interaction between extracellular loops 1 and 2 contributes to Orai1 channel recycling and open up the possibility for therapies targeted to treat diseases like atopic dermatitis." (PMID 31600783, 2020). "Meanwhile, Tribuli Fructus extract could suppress skin inflammation in atopic dermatitis mice through regulating calcium channels and mast cell activation by targeting ORAI-1." (PMID 36712922, 2023). "Therefore, the potent inhibitory effect of Ech A on the Orai1 activity (IOrai1) suggested that the anti-inflammatory action and therapeutic effects of Ech A on atopic dermatitis may be mediated, at least partly, by the inhibition of Ca2+-signaling in the immune cells." (PMID 36827119, 2023). "For instance, patients suffering from atopic dermatitis have recently been identified to show an increase in membrane-resident Orai1, leading to a mismatch in the STIM1-Orai1 stoichiometry that phenotypically culminates in the inhibition of Ca2+ entry and gene expression." (PMID 33466526, 2021).
Autoimmunity (13 papers, 2013 to 2024). The occurrence of an immune reaction against the organism's own cells or tissues. "In vivo, Orai1/Orai2 double-deficient mice have impaired T cell-dependent antiviral immune responses, and are protected from T cell-mediated autoimmunity and alloimmunity in models of colitis and graft-versus-host disease." (PMID 28294127, 2017). "Here the authors show that STIM1 and STIM2, which activate the Ca2+ channel ORAI1, are essential for the differentiation of peripheral Treg cells into tissue-resident and follicular Treg cells and their ability to limit autoimmunity in mice." (PMID 30862784, 2019). "To elucidate the role of Orai1 and Orai2 in autoimmunity, we used an adoptive transfer model of IBD that tests the function of ORAI1 and ORAI2 in pathogenic donor T cells." (PMID 28294127, 2017). "This study demonstrates the feasibility of antibody-mediated inhibition of Orai1 function and, more broadly, reveals the possibility of targeting ion channels with biologics for the treatment of autoimmunity and other diseases." (PMID 24376610, 2013). "Moreover, as described in the literature for PRKDC and ORAI1, mutations within SERPING1 can also cause severe forms of inflammatory and autoimmune disorders." (PMID 36294757, 2022). "Additionally, Orai1 V181SfsX8 and L194P, representing LoF mutations in TM3, lead to autoimmunity and ectodermal dysplasia." (PMID 33333945, 2020). "Autoimmune disorders described in the absence of ORAI1 are associated with inflammation of the CNS." (PMID 34690811, 2021). "Diverse disease-related Orai1 mutants are known to be responsible for the development of SCID, Stormorken-like syndrome, TAM, autoimmunity, and ectodermal dysplasia (EDA)." (PMID 33333945, 2020). "Analysis of mice homozygously expressing nonfunctional Orai1 in the hematopoietic tissue revealed a critical role for Orai1 in T-cell mediated autoimmunity and allograft rejection." (PMID 26789410, 2016). "The lack of ORAI1 in B cells can lead to immunodeficiency and also to autoimmunity." (PMID 34690811, 2021). "However, ablation of STIMs, but not ORAIs, affects thymic development of Tregs and ablation of STIMs, but not ORAI1, results in multi-organ autoimmunity in mice and humans." (PMID 28492364, 2017).
colorectal cancer (11 papers, 2014 to 2025). A primary or metastatic malignant neoplasm that affects the colon or rectum. "In colorectal cancer, higher ORAI1 expression is associated with a more advanced clinical stage, increased metastasis incidence, and shorter overall survival." (PMID 38672434, 2024). "Furthermore, the high expression of ORAI1 enhanced cell proliferation and is associated with poor prognosis in colorectal cancer." (PMID 34055617, 2021). "There are also reports that the degree of Orai1 expression is related to clinical outcomes, as in colorectal cancer and multiple myeloma." (PMID 37759164, 2023). "ORAI1 also regulates EGF-mediated and lipopolysaccharide-mediated PTGS2 gene expression in colorectal cancer cell lines and AGS gastric adenocarcinoma cells, respectively." (PMID 35682546, 2022). "In colorectal cancer cells, exposure to TGF-β1 increases the ORAI1 expression, and ORAI1 mediates the TGF-β induced EMT." (PMID 34988012, 2021). "For example, in colorectal cancer cells, epidermal growth factor (EGF) increased expression of cyclooxygenase-2 via STIM1 and Orai1." (PMID 24586666, 2014). "Furthermore, Orai1 is involved in SOCE-induced proliferation of gastric cancer and colorectal cancer cells, and is also critical for the migration and metastasis of breast tumor cells (Yang, Zhang, and Huang 2009)." (PMID 36310590, 2022). "In conclusion, our results demonstrated that ORAI1 could mediate TGF-β-Induced EMT by promoting Ca2+ entry and calpain activity in Colorectal Cancer Cells." (PMID 34055617, 2021). "have proposed that, during carcinogenesis, colorectal cancer cells may switch from a small, transient SOCE based on ORAI1-dependent CRAC channels (normal cells) to large and sustained currents depending on both ORAI1 and TRPC1 channels (tumor cells)." (PMID 32733237, 2020). "However, the relationship between TGF-β-induced EMT and Ca2+ signaling remains unclear, and the functions of ORAI1-mediated SOCE in the TGF-β-induced EMT in colorectal cancer cells have not been investigated sufficiently." (PMID 34055617, 2021). "However, our observations agree with others reporting that ASA administration impairs STIM1/Orai1 interaction, and hence, ASA reduces SOCE in colorectal cancer cells; meanwhile, other nonsteroidal anti-inflammatory drugs, such as sulindac, impair SOCE and STIM1 membrane translocation." (PMID 41155293, 2025).